NMRAL1 (NmrA like redox sensor 1)
Description:
Redox sensor protein. Undergoes restructuring and subcellular redistribution in response to changes in intracellular NADPH/NADP(+) levels. At low NADPH concentrations the protein is found mainly as a monomer, and binds argininosuccinate synthase (ASS1), the enzyme involved in nitric oxide synthesis. Association with ASS1 impairs its activity and reduces the production of nitric oxide, which subsequently prevents apoptosis. Under normal NADPH concentrations, the protein is found as a dimer and hides the binding site for ASS1. The homodimer binds one molecule of NADPH. Has higher affinity for NADPH than for NADP(+). Binding to NADPH is necessary to form a stable dimer.
Synonyms: HSCARG; FLJ25918; SDR48A1
Tractability: Small molecule: a structure with a bound ligand is known; it has a high-quality binding pocket. PROTAC: ubiquitination databases record sites on it; its protein half-life has been measured.
Gene: Protein-coding gene on chromosome 16 (4,461,684 to 4,495,763, reverse strand). Ensembl gene ENSG00000153406.
Subcellular location: Cytoplasm; Cytoplasm, perinuclear region; Nucleus
Subcellular location (Human Protein Atlas): Nucleoplasm
Pathways (Reactome):
Disease: ASS1 variants cause citrullinemia
Metabolism: Urea cycle
Gene Ontology:
Molecular function: identical protein binding; protein binding
Cellular component: nucleoplasm; cytosol; nucleus; cytoplasm; perinuclear region of cytoplasm
Genetic constraint (gnomAD): Loss-of-function variants: 32 observed, 29.21 expected, observed/expected ratio (o/e) 1.1, 90% interval 0.83 to 1.47. The upper end of that interval is the gene's LOEUF score, 1.47, which puts it in group 6 of 6, group 1 being the genes least tolerant of losing a copy. Missense variants: 420 observed, 410.92 expected, observed/expected ratio (o/e) 1.02, 90% interval 0.94 to 1.11. Synonymous variants: 166 observed, 175.98 expected, observed/expected ratio (o/e) 0.94, 90% interval 0.83 to 1.07.
Homologues: Orthologues: chimpanzee NMRAL1 (99% identical), macaque NMRAL1 (91% identical), dog NMRAL1 (88% identical), pig NMRAL1 (87% identical), rat Nmral1 (86% identical), mouse Nmral1 (85% identical), guinea pig NMRAL1 (81% identical).
Diseases named in the same sentence as NMRAL1 in open-access papers:
NMRAL1 is named in the same sentence as 7 diseases in open-access papers, as found by Europe PMC text mining. Sharing a sentence is not in itself a finding about the gene and the disease. The quoted sentences say what the papers report.
autoimmune disease (2 papers, 2014 to 2024). A disorder resulting from loss of function or tissue destruction of an organ or multiple organs, arising from humoral or cellular immune responses of the individual to their own tissue constituents. "Additionally, we did not include serum samples from patients with other inflammatory or autoimmune diseases, which would have further validated the specificity of NMRAL1 as a biomarker for AS combined with gut inflammation." (PMID 39671362, 2024).
heart failure (1 paper, 2023). Inability of the heart to pump blood at an adequate rate to meet tissue metabolic requirements. "Moreover, expression level of NMRA-like protein NMRAL1 pseudogene (NMRAL2P) is significantly decreased in the right ventricle in heart failure, suggesting that NMRAL2P is involved in heart failure." (PMID 37491351, 2023).
mammary tumor (1 paper, 2024). "They found that compared with wild type or heterozygous PyMT mice, PyMT transgenic mice with NMRAL1 gene knockout show delayed mammary tumor occurrence." (PMID 39671362, 2024).
cancer (1 paper, 2024). A tumor composed of atypical neoplastic, often pleomorphic cells that invade other tissues. "In addition, NMRAL1 has a close biological relationship with cancer." (PMID 39671362, 2024).
NMRAL1 also shares sentences with these, for which no sentence is quoted: viral infection (4 papers); schizophrenia (3); Coronary Heart Disease (1).